ATP10D (ATPase phospholipid transporting 10D (putative))
Description:
Catalytic component of a P4-ATPase flippase complex, which catalyzes the hydrolysis of ATP coupled to the transport of glucosylceramide (GlcCer) from the outer to the inner leaflet of the plasma membrane.
Synonyms: ATPVD; KIAA1487
Tractability: Antibody: UniProt places it where antibodies can reach, with high confidence; its Gene Ontology location is reachable by antibodies, with high confidence; UniProt predicts a signal peptide or a membrane-spanning region; the Human Protein Atlas places it where antibodies can reach. PROTAC: ubiquitination databases record sites on it.
Gene: Protein-coding gene on chromosome 4 (47,485,275 to 47,593,486, forward strand). Ensembl gene ENSG00000145246.
Subcellular location: Cell membrane; Endoplasmic reticulum membrane
Subcellular location (Human Protein Atlas): Nucleoplasm; Plasma membrane
Pathways (Reactome):
Transport of small molecules: Ion transport by P-type ATPases
Gene Ontology:
Molecular function: ATPase-coupled intramembrane lipid transporter activity; glycosylceramide flippase activity; protein binding; ATP binding; magnesium ion binding; ATP hydrolysis activity; nucleotide binding
Biological process: monoatomic cation transport; monoatomic ion transmembrane transport; phospholipid translocation; phospholipid transport
Cellular component: endoplasmic reticulum; endoplasmic reticulum membrane; phospholipid-translocating ATPase complex; plasma membrane; membrane
Genetic constraint (gnomAD): Loss-of-function variants: 81 observed, 137.84 expected, observed/expected ratio (o/e) 0.59, 90% interval 0.49 to 0.71. The upper end of that interval is the gene's LOEUF score, 0.71, which puts it in group 2 of 6, group 1 being the genes least tolerant of losing a copy. Missense variants: 1,526 observed, 1,719.9 expected, observed/expected ratio (o/e) 0.89, 90% interval 0.85 to 0.93. Synonymous variants: 541 observed, 618.37 expected, observed/expected ratio (o/e) 0.87, 90% interval 0.81 to 0.94.
Homologues: Orthologues: chimpanzee ATP10D (99% identical), macaque ATP10D (96% identical), pig ATP10D (88% identical), dog ATP10D (85% identical), rabbit ATP10D (85% identical), guinea pig ATP10D (84% identical), rat Atp10d (83% identical), mouse Atp10d (83% identical), tropical clawed frog atp10d (62% identical), zebrafish atp10d (51% identical), Drosophila melanogaster CG4301 (26% identical), Drosophila melanogaster CG9981 (23% identical), and 3 more. Paralogues in human: ATP10A (49% identical), ATP10B (49% identical), ATP8B2 (31% identical), ATP8B1 (30% identical), ATP8B4 (30% identical), ATP8A2 (30% identical), ATP8A1 (28% identical), ATP8B3 (28% identical), ATP11B (27% identical), ATP11A (27% identical), ATP11C (26% identical), ATP9B (22% identical), and 1 more.
Diseases named in the same sentence as ATP10D in open-access papers:
ATP10D is named in the same sentence as 20 diseases in open-access papers, as found by Europe PMC text mining. Sharing a sentence is not in itself a finding about the gene and the disease. The quoted sentences say what the papers report.
Obesity (5 papers, 2009 to 2025). Accumulation of substantial excess body fat. "ATP10D has also been implicated in obesity and hyperinsulinemia in mice." (PMID 23579954, 2013). "We also identified the gene atp10d (Phospholipid-transporting ATPase VD), which has been shown to improve insulin sensitivity and reduce the chance of developing obesity in mice fed a high-fat diet." (PMID 39151124, 2024). "Atp10d is mutated (i.e., a premature stop codon in exon 12) in C57BL/6J mice, which have a predisposition to develop obesity, hyperglycemia and hyperinsulinemia when placed on a high-fat diet." (PMID 23579954, 2013). "Mutations of ATP10D (C57BL/6J(B6)) in mice result in low HDL concentrations and these mice develop severe obesity, hyperglycaemia and hyperinsulinaemia when fed on a high-fat diet." (PMID 19798445, 2009). "In male offspring, associated dmCpGs were linked to known obesity-related genes including B4GALNT4 (cg25020933, cg15762098), ADCY9 (insulin secretion and thyroid hormone synthesis) (cg00610508), ADRB1 (cg13848598) and ATP10D (cg14009629)." (PMID 40410506, 2025). "In mice Atp10d is associated with HDL modulation and C57BL/6 mice expressing a truncated, non-functional form of ATP10D easily develop obesity and insulin resistance on high-fat diet." (PMID 28542499, 2017).
Insulin resistance (4 papers, 2009 to 2024). Increased resistance towards insulin, that is, diminished effectiveness of insulin in reducing blood glucose levels. "TSSK4 appears to have a rather specialized role for male fertility while sequence variants in ATP10D have been demonstrated to significantly associate with metabolic disorders including insulin resistance." (PMID 29351342, 2018). "Although it is uncertain whether these variants cause functional impairments in ATP10D, the ATP10D variants are also associated with the increased risk of insulin resistance, myocardial infarction, and atherosclerosis." (PMID 38280458, 2024). "Based on the mouse model, increased circulating glucosylceramides in connection with ATP10D function would be one plausible mechanism of contributing to weight gain and early insulin resistance." (PMID 19798445, 2009).
atherosclerosis (3 papers, 2022 to 2024). A disease characterized by the build-up of fatty material and calcium deposition in the arterial wall resulting in partial or complete occlusion of the arterial lumen. "Some mutated genes are related to atherosclerosis, such as FAAH, KALRN, ATP10D, CUBN, APOA5, and LRP1." (PMID 36071494, 2022). "The mechanism for how GlcCer transport by ATP10D influences metabolism and atherosclerosis remains unclear." (PMID 38382846, 2024). "Additionally, GWA studies have implicated ATP10A and ATP10D in insulin resistance, HDL homeostasis, and atherosclerosis, suggesting that these flippases influence liver metabolism." (PMID 38382846, 2024).
bladder carcinoma (1 paper, 2021). "Three of the novel missense mutational cancer genes were mutated at >1% in their respective TCGA cancer types: ATP10D (9.4% in melanoma), SVIL (3.2% in ovarian carcinoma) and WDR36 (3.2% in bladder carcinoma)." (PMID 34313788, 2021).
coronary artery disease (1 paper, 2022). "The SNPs in KALRN (rs9289231), ATP10D (rs2351791), CUBN (rs2291521), and APOA5 (Rs662799) are all significantly associated with the risk of coronary artery disease (CAD)." (PMID 36071494, 2022).
Gaucher disease (1 paper, 2024). Gaucher disease (GD) is a lysosomal storage disorder encompassing three main forms (types 1, 2 and 3), a fetal form and a variant with cardiac involvement (Gaucher disease - ophthalmoplegia - cardiovascular calcification or Gaucher-like disease). "Moreover, the expression of GlcCer flippases, including ATP10D, also reduced cellular hexosylceramide levels in fibroblasts derived from patients with Gaucher disease, which is a lysosomal storage disorder with excess GlcCer accumulation." (PMID 38280458, 2024).
Infertility (1 paper, 2024). "Therefore, ATP10A deficiency alone is sufficient to cause the male-specific infertility phenotypes in mice and this suggests that the specific ATP10A substrate critical for male fertility might be PC and not GlcCer; because ATP10A flips both PC and GlcCer and ATP10D only flips GlcCer." (PMID 38415274, 2024).
lung carcinoma (1 paper, 2018). "ATP10D has not previously been related to lung cancer or other tumors." (PMID 29766673, 2018).
metabolic disorders (3 papers, 2018 to 2024). "C57BL/6 J mice, a popular mouse strain used in metabolic studies due to their susceptibility to metabolic disorders, have a premature stop codon in Atp10D and is therefore an Atp10D null mouse." (PMID 38382846, 2024). "ATP10D single-nucleotide polymorphisms are associated with GlcCer elevation in plasma, and both ATP10A and ATP10D are linked to metabolic disease." (PMID 34597626, 2021).
cardiovascular diseases (1 paper, 2009). "From the novel association of SNPs in ATP10D to MI seen in German studies, further investigation of the specific role of glucosylceramides in MI and other cardiovascular diseases is warranted." (PMID 19798445, 2009).
ATP10D also shares sentences with these, for which no sentence is quoted: cancer (2 papers); gynecologic cancer (1); hyperglycaemia (1); Hyperinsulinemia (1); lysosomal storage disorder (1); male infertility (1); melanoma (1); myocardial infarction (1); ovarian carcinoma (1); tumor (1).